MGMT (O-6-methylguanine-DNA methyltransferase)
Diseases named in the same sentence as MGMT in open-access papers (continued):
Sharing a sentence is not in itself a finding about the gene and the disease.
glioblastoma (continued). "Promoter methylation of MGMT reflects epigenetic silencing associated with longer survival in patients with glioblastoma treated using alkylating agents." (PMID 34654402, 2021). "This retrospective cohort study of surgical patients diagnosed with glioblastoma in Scotland (UK) showed that MGMT promoter methylation was associated with better survival, but this effect was lost in patients aged ≥65 years old." (PMID 34988453, 2021). "Previously, chemoresistance to TMZ in glioblastoma cells was mainly associated with MGMT methylation status." (PMID 33525678, 2021). "MGMT promoter methylation typically causes reduced levels of MGMT in glioblastoma cells and makes them susceptible to alkylating agents." (PMID 34771592, 2021). "Our results concluded that IDH1 mutation and MGMT gene promoter methylation are considered independent prognostic factors in glioblastoma." (PMID 34257620, 2021). "In elderly glioblastoma patients with MGMT promoter-methylated glioblastoma, TMZ chemotherapy was associated with a longer event-free survival and a trend towards longer overall survival (OS) as compared to radiation therapy alone." (PMID 32748120, 2021). "This revealed that IDH1 mutation and MGMT methylation are independent prognostic factors in glioblastoma." (PMID 34257620, 2021). "In a post hoc analysis of a phase III trial, MGMT promoter methylation was associated with a 2-year survival increase in TMZ-treated glioblastoma patients from 14 to 46%." (PMID 33001310, 2021). "The promoter CpG island hypermethylation associated gene silencing of MGMT is involved in a wide spectrum of human cancers, including glioblastoma, gastric, colon, and ovarian." (PMID 34134626, 2021). "The MGMT gene is associated with DNA repair, and its methylation produces gene silencing, allowing glioblastoma patients receiving chemotherapy to achieve a better prognosis." (PMID 34781885, 2021). "In the literature, higher levels of gene body cytosine modification were correlated with higher MGMT expression levels, and also associated with glioblastoma treatment response." (PMID 33588926, 2021). "The association between IDH1 mutation and MGMT methylation status with recurrence-free interval within 3 years among glioblastoma patients treated with radiotherapy or chemoradiotherapy." (PMID 34257620, 2021). "For instance, epigenetic silencing of MGMT is associated with an improved response to chemotherapy in glioblastoma patients through the deactivation of crucial DNA repair mechanisms." (PMID 34417465, 2021). "The methylation of the MGMT promoter is a prognostic factor associated with increased temozolomide response and overall survival in glioblastoma." (PMID 33680961, 2021). "The relationship between age, IDH1 mutation, and MGMT promoter methylation in glioblastoma patients and one-year recurrence-free interval." (PMID 34257620, 2021). "The regulation of the MGMT gene by miR-181d was found after transfection of this miRNA in glioblastoma cell lines, as the transfection caused a reduction in the expression of the MGMT gene as well as the MGMT protein." (PMID 34873501, 2021). "Some studies have shown that the resistance of human glioblastoma cells (GBM8901) to temozolomide (TMZ) is associated with the expression of O6-methylguanine-DNA-methyltransferase (MGMT), while TMZ-induced autophagy depends on the expression of MGMT." (PMID 33494431, 2021). "Our data underline the impact of the MGMT promoter methylation status in the treatment response of IDH-wildtype glioblastoma." (PMID 34185258, 2021). "We also assessed the implications of the association between MGMT methylation and vascularity on the benefit of extending temozolomide treatment in different groups of glioblastoma patients." (PMID 34771583, 2021).
glioblastoma (continued). "A meta-analysis of 34 clinical trials concluded that MGMT methylation was significantly associated with better overall survival in patients with glioblastoma." (PMID 33661424, 2021). "MGMT promotor methylation is associated with an improvement in overall survival in patients suffering from glioblastoma and influences the overall survival of patients with LGG." (PMID 32158691, 2020). "(Hyper-)methylation of the MGMT promoter (O6-Methylguanin DNA-Methyltransferase), a gene encoding a DNA repair protein removing alkyl adducts, constitutes a favourable factor in glioblastoma response to temozolomide." (PMID 32260145, 2020). "One of the molecular markers with the highest prognostic/predictive impact in glioblastoma is the methylation status of the promoter of the O6-methylguanine DNA methyltransferase (MGMT) gene, which encodes for an enzyme involved in the DNA repair system." (PMID 33194592, 2020). "Resveratrol potentiates the effects of temozolomide on glioblastoma cells by negatively regulating the NF-κB pathway and thereby causing a reduction in MGMT expression." (PMID 33330091, 2020). "TERT-mutated glioblastoma (GBM) patients with MGMT methylation benefited from temozolomide (TMZ) treatment (HR = 0.33; 95% CI = 0.23–0.47; p-value < 0.001)." (PMID 32957941, 2020). "Isocitrate dehydrogenase (IDH1/2) mutations and O6-alkylguanine DNA methyltransferase (MGMT) promoter methylations are acknowledged survival predictors in patients with glioblastoma (GB)." (PMID 34966832, 2020). "On top, studies investigating the impact of CE and NCE resection have reported limited molecular data on IDH mutation and MGMT promoter methylation of their studied glioblastoma population." (PMID 32766140, 2020). "We also performed IDH mutational and MGMT promoter methylation analyses on all glioblastoma included in our cohort." (PMID 32766140, 2020). "MGMT has been reported to be associated with tumor growth and metastasis in patients with glioblastoma and cholangiocarcinoma." (PMID 33033516, 2020). "This cell line is the only one among the indicated cells that expresses the DNA-repairing enzyme O6-methylguanine–DNA methyltransferase (MGMT) that removes the alkylation caused by temozolomide, a first-line key drug in glioblastoma treatment." (PMID 33291321, 2020). "Of note, increased MGMT expressions have been associated with TMZ resistance in glioma stem-like cells as well as in glioblastoma xenograft models." (PMID 33318498, 2020). "It has been shown that TMZ, in addition to causing direct DNA damage, limits repair by downregulating MGMT expression in some glioblastoma cell lines." (PMID 33201894, 2020). "miR-200a-3p has also been found to interact with MGMT to increase susceptibility of glioblastoma to chemotherapy drugs." (PMID 32086739, 2020). "In literature, age of patients, performance status, IDH (isocitrate dehydrogenase) mutation, MGMT (O6 Methylguanine-DNA methyltransferase) methylation status, and treatment were commonly known as predictive factors for survival in glioblastoma." (PMID 33247700, 2020). "Glioblastoma patients with chromosome 10q loss associated with hypermethylation of MGMT promoter had significantly longer overall survival (OS) (P = .0024) and progression‐free survival (PFS) (P = .031)." (PMID 32666673, 2020). "In this paper we reported the analysis of patient overall survival (OS) in associations with PD-L1, IDH1 and MGMT status in anaplastic astrocytoma and glioblastoma patient receiving standard therapy." (PMID 33282092, 2020).
glioblastoma (continued). "Epigenetic silencing of the MGMT gene by promoter methylation has been associated with longer overall survival in patients with glioblastoma who received alkylating chemotherapy with TMZ." (PMID 33363021, 2020). "Some studies found that liver-type glutaminase (LGA), which is transfected and expressed in human glioblastoma cell lines, causes a decrease in MGMT expression, and also increases sensitivity of glioblastoma to chemotherapy drugs." (PMID 32086739, 2020). "The aim of our study was to screen Serbian patients with primary glioblastoma for an MGMT promoter hypermethylation and to evaluate its associations with overall survival (OS) and sensitivity to temozolomide (TMZ) treatment." (PMID 30717206, 2019). "Methylation of the MGMT promoter region is associated with silencing of gene expression, and occurs in about 40–50% of glioblastoma cases." (PMID 30967140, 2019). "The methylation sites and frequencies of CpG islands vary among MGMT-deficient tumor cell lines, xenografts of glioblastoma and in situ glioblastoma." (PMID 32010632, 2019). "Prior studies demonstrated that clinical factors including age and extent of tumor resection as well as O6-methylguanine-DNA methyltransferase (MGMT) promoter methylation status were prognostic factors associated with glioblastoma." (PMID 31150499, 2019). "The methylation sites and frequencies of CpG islands vary in MGMT-deficient tumor cell lines, xenografts of glioblastoma and in situ glioblastoma." (PMID 32010632, 2019). "Significantly increased ADC value (P < 0.001) and decreased rCBF (P < 0.001) were associated with MGMT promoter methylation in primary glioblastoma." (PMID 29467012, 2018). "MGMT (methyl guanine DNA methyl transferase) is associated with several cancer types, including colorectal cancer, lung cancer, and glioblastoma." (PMID 29691341, 2018). "Epigenetic silencing of the MGMT gene can be detected in around half of the glioblastoma cases and is associated with increased survival in patients receiving alkylating agents." (PMID 29515653, 2018). "Promoter hypermethylation of MGMT (O6-methylguanine-DNA methyltransferase) gene have been associated with response to alkylating chemotherapy is an established biomarker for the alkylation therapy of glioblastoma." (PMID 30374421, 2018). "MGMT promoter methylation is reported in 30–60% of patients with glioblastoma and is associated with an increased sensitivity to TMZ, a better clinical response to TMZ and a prolonged survival." (PMID 30248992, 2018). "For single-gene loci, hypermethylation of CDKN2A in colorectal cancer, MGMT in glioblastoma, BRCA1 in breast cancer were reported to be associated with poor clinical outcomes." (PMID 30217224, 2018). "Compared to the wild type of homozygous C, glioblastomas that carry the T allele of rs16906252, i.e. heterozygous C and T or homozygous T alleles, showed hyper-methylated MGMT promoters and a better survival outcome." (PMID 28575062, 2017). "The evaluation of MGMT protein in the tumor cells using immunohistochemistry (IHC) was the diagnostic standard in glioblastoma pathology during the observation period." (PMID 27554774, 2017). "Previous studies suggested that the rs16906252 T allele results in reduced promoter activity and MGMT expression and is associated with MGMT methylation in glioblastoma, colorectal cancer, and in a subset of malignant pleural mesothelioma patients." (PMID 28575062, 2017). "Epigenetic silencing of the DNA repair gene MGMT by promoter methylation compromised DNA repair and was associated with longer survival in glioblastoma patients treated with alkylating agents." (PMID 28730141, 2017). "Previous studies showed that glioblastoma patients carrying the T allele with hyper-methylated MGMT promoter had significantly better prognosis." (PMID 28575062, 2017).
glioblastoma (continued). "Even glioblastomas with favorable molecular profiles characterized by isocitrate dehydrogenase 1 or 2 mutation or O6-methylguanine DNA methyltransferase (MGMT) promoter methylation are prone to fail therapy." (PMID 26887050, 2016). "Future perspectives in neuro-oncology will bring the concurrent assessment of IDH1/2 mutations and MGMT promoter methylation status for glioblastoma and 1p/19q co-deletion for oligodendroglioma." (PMID 27379174, 2016). "The methylation of MGMT promoter has a direct clinical consequence, as it is associated with longer overall survival in patients with glioblastoma, who undergo a combination treatment consisting of radiotherapy and an alkylating agent (such as temozolomide)." (PMID 27891063, 2016). "Low level of MGMT expression in glioblastoma is associated with favourable response to the alkylating drug temozolomide in patients." (PMID 27057640, 2016). "The methylation of MGMT promoter is another factor that is associated with survival of glioblastoma patients." (PMID 27891063, 2016). "MGMT promoter methylation occurs in 40% of primary glioblastoma and is associated with an increased survival after radiotherapy and chemotherapy with temozolomide." (PMID 27253461, 2016). "This type of analysis successfully elucidated the preferred locations of IDH1/2 mutated and MGMT promoter methylated glioblastoma." (PMID 27716832, 2016). "Glioblastomas and stage IV melanomas with MGMT methylation respond better to treatment with alkylating agents (temozolomide and dacarbazine), and MGMT methylation is an independent variable associated with disease-free and overall survival." (PMID 26506390, 2015). "Of the 274 patients enrolled in this study, the status of IDH1/2 mutation and MGMT promoter methylation was analyzed in 229 glioblastomas." (PMID 26503470, 2015). "The importance of IDH mutations and MGMT promoter methylation as biomarkers for glioblastoma patient is widely recognized." (PMID 26503470, 2015). "Our study demonstrates that IDH and MGMT promoter methylation status independently associate with favorable outcome in TMZ+RT treated glioblastoma patients." (PMID 26503470, 2015). "Multivariate analysis showed that KPS and MGMT promoter methylation were also independently associated with OS in glioblastoma." (PMID 26341881, 2015). "IDH1 mutation, MGMT promoter methylation, and gene expression profiling can segregate newly diagnosed glioblastoma patients into groups with different prognoses." (PMID 26646075, 2015). "Epigenetic silencing of the MGMT DNA-repair gene by promoter methylation compromises DNA repair and has been associated with longer survival in patients with glioblastoma who receive alkylating agents and temozolomide." (PMID 25695077, 2015). "Our study demonstrates IDH mutation and MGMT promoter methylation status independently associate with favorable outcome in TMZ+RT treated glioblastoma patients." (PMID 26503470, 2015). "We constructed a novel diagnostic system to predict the prognosis of glioblastoma patients using information regarding the methylation status of the entire MGMT promoter region." (PMID 25175833, 2014). "O-6-methylguanine-DNA methyltransferase (MGMT) has been associated with resistance to alkylating agent cancer therapy in Glioblastoma (GBM), the most common and aggressive primary brain tumor in adults." (PMID 26150933, 2014). "While MGMT promoter status has been associated with therapeutic response to temozolomide for glioblastoma patients, there has been reluctance to restrict temozolomide treatment to patients harboring MGMT promoter methylated glioblastomas." (PMID 24994119, 2014).
glioblastoma (continued). "A significantly higher MGMT promoter methylation in carriers of the T allele has been described recently in glioblastoma, diffuse large B-cell lymphoma, colorectal carcinoma, pleural mesothelioma, and lung cancer." (PMID 24380367, 2013). "Because of a strong association with the MGMT methylation in glioblastoma and further tumors like colorectal carcinoma, pleural mesothelioma, and lung cancer, the MGMT C-56 T polymorphism was included in our study." (PMID 24380367, 2013). "Promoter methylation of MGMT leads to epigenetic silencing of the MGMT and this compromises DNA repair and has been associated with improved outcomes in patients with glioblastoma who receive alkylating agents." (PMID 22553975, 2012). "Epigenetic silencing of the MGMT gene, encoding a DNA repair enzyme, has been recently found to be of predictive value in glioblastoma." (PMID 22672670, 2012). "Epigenetic silencing of the MGMT gene by promoter methylation of CpG islands was recently associated with prolonged survival of patients with glioblastoma who received TMZ in combination with radiotherapy." (PMID 20736948, 2010). "Epigenetic silencing of O6-methylguanine-DNA-methyltransferase (MGMT) by promoter methylation is associated with improved survival in glioblastomas treated with alkylating agents." (PMID 19536096, 2009). "Although numerous studies have reported associations between MGMT and survival in glioblastomas treated with alkylating agents, few reports support the findings of EORTC 26981/22981 & NCIC CE.3 in large cohorts treated with temozolomide and radiotherapy." (PMID 19536096, 2009). "Due to the predictive significance of MGMT promoter methylation and the establishment of global DNA‐methylation based classification of CNS tumors, DNA methylation arrays are now often recommended as a standard diagnostic tool for glioblastoma." (PMID 40527506, 2026). "for example, showed a substantial correlation between it and temozolomide responsiveness and Later meta-analyses have confirmed that in glioblastoma patients after alkylating chemotherapy, MGMT methylation is associated with better overall and progression-free survival." (PMID 41311621, 2025). "MGMT promoter methylation inactivates the expression of MGMT and has been associated with longer patient survival and tumor response to temozolomide chemotherapy in patients with glioblastoma." (PMID 40277764, 2025). "The aim of this study was to investigate the association of gliomas' main genetic markers: isocitrate dehydrogenase (IDH) mutations and O6-methylguanine-DNA methyltransferase (MGMT) promoter methylation status with the survival rate in Russian patients with glioblastoma and other glial tumors." (PMID 40377745, 2025). "MGMT promoter methylation: Methylation of the MGMT (O6-methylguanine-DNA methyltransferase) promoter is associated with an improved response to temozolomide chemotherapy, leading to a more favorable prognosis in glioblastoma patients." (PMID 38337543, 2024). "Tumor shape complexity appears to be an independent prognostic factor in glioblastoma patients and may also be associated with MGMT promoter methylation status and extent of surgical resection." (PMID 39531176, 2024). "PARP inhibitors may introduce novel poly(ADP-ribosyl)ation modifications to MGMT, thereby neutralizing its function and enhancing the susceptibility of MGMT wild-type glioblastoma to temozolomide-induced cytotoxicity." (PMID 39055560, 2024). "It is the promoter methylation of the MGMT (O6-methylguanine-DNA methyltransferase) DNA-repair gene, resulting in its silencing, which has been associated with longer survival in patients with glioblastoma who receive alkylating agents." (PMID 39273414, 2024).